TRPC5 (transient receptor potential cation channel subfamily C member 5)
Diseases named in the same sentence as TRPC5 in open-access papers (continued):
Sharing a sentence is not in itself a finding about the gene and the disease.
tumor (30 papers, 2015 to 2025). "The levels of exosome-carrying TRPC5 were significantly associated with the expression of TRPC5 in BC tissues and tumor response to chemotherapy." (PMID 35582044, 2020). "Mutation frequencies of TRPC5 in the studied tumor entities were analyzed using cBioPortal data." (PMID 40723382, 2025). "Additionally, TRPC5-mediated exosome secretion is linked to the activation of P-glycoprotein and Wnt/β-catenin signaling, both of which contribute to enhanced tumor survival and intercellular communication under therapeutic pressure." (PMID 40813985, 2025). "In contrast, our previous studies have suggested that EA is a potent and selective activator of canonical transient receptor potential channel 4 (TRPC4) and 5 (TRPC5), and we have proposed that EA causes anti-tumor cell activity by Na+ loading into cells through heteromeric TRPC4/C1 channels." (PMID 29209034, 2017). "This study addresses a gap in the field, as there is currently limited research on TRPC5, particularly regarding its potential role as a tumor marker." (PMID 40723382, 2025). "Immunostaining of CRC tissue specimens further revealed that high TRPC5 and FAP expressions were significantly associated with worse tumor regression." (PMID 38817851, 2024). "The analysis revealed a significant upregulation of TRPC5 expression in tumor tissues compared to adjacent normal tissues." (PMID 39309444, 2024). "A substance called englerin A, isolated from the African plant phyllanthus engleri, can activate the ion channels TRPC4 and TRPC5 at nanomolar concentrations and it can inhibit the growth of tumor cell lines expressing high levels of TRPC4 or TRPC5." (PMID 36674553, 2023). "TRPC5 is a Ca2+-activated ion channel that is regulated by components of the tumour microenvironment, such as acidosis and supports hypoxia responses." (PMID 35806388, 2022). "Remarkably, lentiviral injection of an shRNA against TRPC5 at tumor sites reverses chemoresistance to doxorubicin and paclitaxel resulting in tumor regression." (PMID 36158191, 2022). "In the present study, the level of circulating EVs carrying TRPC5 (cirExo-TRPC5) was significantly correlated with TRPC5 expression levels in BC tissues and tumour response to chemotherapy." (PMID 35053279, 2022). "TRPC5 protein expression by CTC was examined using immunofluorescence, while TRPC5 expression in the tumor tissue from the same patient was examined using immunohistochemistry." (PMID 34422911, 2021). "Further, in nude mice bearing doxorubicin-resistant tumor xenografts, there is increased expression of TrpC5 proteins and high levels of TrpC5-positive circulating EVs, as compared to doxorubicin-sensitive tumor xenografts." (PMID 33920605, 2021). "This study discovered that the TRPC5 level in tumor cells of CRC in situ was significantly correlated with the CTC-TRPC5 level in peripheral blood." (PMID 34422911, 2021). "In conclusion, englerin can activate TRPC4 and TRPC5 ion channels at nanomolar concentrations, and englerin A can inhibit growth of tumor cell lines which express high levels of TRPC4 or TRPC5." (PMID 26098886, 2015). "Hence, this study gives rise to future research on the role of TRPC5 in tumor progression and metastasis, especially since BCCs, which rarely metastasize, are predominantly negative for TRPC5 and multiple other pH-sensitive proteins." (PMID 40723382, 2025). "As TRPC5 is sensitive to local pH changes, it is particularly relevant in the context of the tumor microenvironment, and maybe also in tumor growth and spread." (PMID 40723382, 2025). "New studies show that TRPC5 is also sensitive to oxidative stress in the tumor microenvironment." (PMID 40723382, 2025). "Furthermore, it limits the proliferation of tumor cell lines with an increased TRPC4/TRPC5 presence." (PMID 40723382, 2025).
tumor (continued). "Additionally, this study lays the groundwork for future research into the role of TRPC5 in tumor progression and metastasis, especially since BCCs, which rarely metastasize, are predominantly negative for TRPC5." (PMID 40723382, 2025). "The suppression of TRPC5 activity as well as of P-gp expression reduced drug resistance and tumor growth both in vitro and in vivo suggesting that inhibiting either P-gp or TRPC5 could be an attractive strategy to overcome drug resistance." (PMID 35814425, 2022). "This suggested that CTC-TRPC5 level could act as the real-time monitoring of TRPC5 expression of tumor cells in situ." (PMID 34422911, 2021). "Remarkably, TRPC5-based chemoresistance could be shuttled to tumor endothelial via intercellular communication." (PMID 29324706, 2018). "Adriamycin-resistant MCF-7 cells could pack the up-regulated TRPC5 channels into mobile extracellular vesicles (EVs), which are released in tumor microenvironment and transferred their signaling content to surrounding endothelial cells." (PMID 29324706, 2018). "However, whether these effects on tumor migration are dependent on the impact of TRPC5 and TRPC6 activity on cell contractility and motility remains to be clarified." (PMID 33132914, 2020). "These differential expression patterns highlight TRPC5 as a potential histological marker for distinguishing BCC from SCC and underscore the need for further studies to elucidate its functional role in tumor progression." (PMID 40723382, 2025). "Recent studies have elucidated the crucial role of TRP channels, specifically TRPC3,TRPC5,TRPV4 TRPML3, in regulating the release, cargo content, and downstream effects of cancer-derived exosomes within the tumor microenvironment (TME)." (PMID 40813985, 2025). "TRPC5, a pH-sensitive member of this family, may act as a signaling molecule in the altered microenvironment of solid tumors, which are characterized by an inverted pH-gradient—with decreased extracellular and increased intracellular pH—that promotes tumor progression." (PMID 40723382, 2025). "Different levels of TRPC5 and GLUT1 protein were observed in tumor tissues from different CRC patients." (PMID 29463225, 2018). "In contrast, TRPC5, TRPV1, and TRPV2 channels have been found to impede macrophage differentiation, suppress HCC cell proliferation, and ultimately decrease tumor cell invasiveness through the Akt/IκB/NF-κB signaling pathway, STAT3 pathway, and Akt/Nrf2 signaling pathway, respectively." (PMID 37569884, 2023). "Additionally, TRPC5-mediated Ca2+ entry promoted transcription of HIF-1α gene, thereby boosting VEGF release and enhancing tumor angiogenesis." (PMID 29324706, 2018). "Furthermore, P-gp production was enriched in tumor endothelium of adriamycin-resistant MCF-7 xenografts than in other sites and was sensitive to TRPC5 inhibition with a specific siRNA (siTRPC5)." (PMID 29324706, 2018). "Specifically, EVs from drug-resistant tumor cells can horizontally transfer various components, such as drug-efflux pumps (e.g., ABCB1, ABCC1), miRNAs (e.g., miR-21-5p, miR-222), and regulatory proteins (e.g., TrpC5, EGFR), to drug-sensitive cells, thereby spreading a drug-resistant phenotype." (PMID 39403600, 2024). "We screened eight different types of tumor and non-tumor cells derived from human tissues by evaluating the TRPC4 mRNA gene expression with quantitative PCR and measuring the functional expression of Ca2+-permeable TRPC4 and/or TRPC5 with Ca2+-response to 30 nM EA." (PMID 29209034, 2017). "For example, TRPC5 was not identified as a target hypothesis because TRPC5 is rarely overexpressed in tumor cell lines." (PMID 26098886, 2015). "However, the exact role of TRPC5 in the chemoresistant tumor microenvironment was not evaluated." (PMID 38817851, 2024).
kidney disease (15 papers, 2016 to 2025). "We demonstrated the podocyte-protective effects of small-molecule inhibitors of TRPC5 channels in human podocytes and kidney organoids, establishing these systems as reproducible, human-specific tools to study podocyte-associated kidney diseases." (PMID 34621762, 2021). "Considering their prominent role in lung and kidney diseases, TRPC5 and TRPC6 have emerged as the most promising therapeutic targets." (PMID 41118703, 2025). "In fact, a TRPC5 inhibitor has entered a phase 2 clinical trial for treating severe forms of kidney disease, supporting consideration of TRPC5 as a therapeutic target of clinical usefulness." (PMID 40003900, 2025). "Among these genes, Adora2b, Trpc5, Ar, Xrcc2, and Atp1b1 are involved in renal disease and blood pressure regulation." (PMID 37125041, 2023). "Genetic deletion or selective inhibition of TRPC5 channels with small-molecule inhibitors protects podocytes in rodent models of kidney disease, but less is known about the human relevance and translatability of TRPC5 inhibition." (PMID 34621762, 2021). "Another TRPC5 inhibitor GFB-887 developed by Goldfinch Bio is in phase 1 clinical trial for the treatment of kidney disease (NCT number: NCT03970122)." (PMID 33683200, 2021). "On the basis of these publications, further studies will be necessary to elucidate the role of TRPC5 in kidney diseases." (PMID 31877991, 2019). "AC1903, A small-molecule inhibitor of TRPC5, suppressed severe proteinuria and prevented podocyte loss in a rat model of hypertensive proteinuric kidney disease, which indicates TRPC5 inhibitors may be valuable for the treatment of progressive kidney diseases." (PMID 33467659, 2021). "A discussion proposed that TRPC5 mutation has not been identified in human kidney diseases, which means the role of TRPC5 in podocyte injury and kidney disease remains to be clarified." (PMID 33921219, 2021). "Interestingly, Adora2b, which mediates renal AMP-activated protein kinase (AMPK) activation, and Trpc5, whose abnormal expression was suggested to interfere with progressive kidney diseases, were subsequently altered at the methylation level due to postnatal protein restriction." (PMID 37125041, 2023). "Critically, data from three chemically distinct compounds that block TRPC5 activity (AC1903, ML204, and GFB-8438) have demonstrated beneficial effects when applied to rodent models of kidney disease." (PMID 34621762, 2021). "Although TRPC5 and TRPC6 have received the most attention, accumulating evidence suggests that TRPC3 also plays a role in kidney diseases." (PMID 31877991, 2019). "Furthermore, through its ability to inhibit TRPC5, AC1903 has been demonstrated to produce in vivo therapeutic effects in different animal models of kidney disease, an improving effect shared by other TRPC5 inhibitors in rats." (PMID 40003900, 2025). "To date, the role of TRPC5 in the normal function of the kidney and in the pathogenesis of kidney disease is not clear." (PMID 35805070, 2022). "The podocyte dysfunction in kidney diseases also implicates another TRPC family member, TRPC5." (PMID 33377622, 2021). "However, a recent study found that TRPC5 was not involved in the occurrence or aggravation of kidney disease." (PMID 33921219, 2021). "However, a role of TRPC5 in progressive kidney disease was not supported by a study with transgenic mice overexpressing either wild-type TRPC5 or a dominant-negative TRPC5 mutant." (PMID 29865154, 2018). "However, protective effects of pharmacological TRPC5 inhibition have not been seen by all investigators, and the over-expression of either wild-type or dominant-negative TRPC5 channels in glomeruli does not appear to induce kidney disease, in contrast to what is seen with over-expression of TRPC6." (PMID 35805070, 2022). "However, results from previous reports have not consistently indicated whether and how TRPC5 plays a role in the development or protection of kidney disease." (PMID 33377622, 2021).
kidney disease (continued). "While we observed that TRPC5 abundance was not altered in the chronic PAN model or in Trpc6del/del rats, it is possible that TRPC5 is more important in other forms of kidney disease or in other experimental models." (PMID 29785489, 2018). "This review highlights the data implicating TRPC6 and other TRPC family members in both genetic and non-genetic forms of kidney disease, focusing on TRPC3, TRPC5, and TRPC6 in a cell type (glomerular podocytes) that plays a key role in proteinuric kidney diseases." (PMID 31877991, 2019).
cardiovascular disease (2 papers, 2019 to 2024). "TRPC5′s significance in cardiovascular disease has received a lot of attention in recent years." (PMID 38703717, 2024).
neurological disorders (2 papers, 2023). "Previous studies have revealed the critical involvement of TRPC4 and TRPC5 in a host of neurological disorders." (PMID 37765099, 2023). "In the hippocampus, TRPC5 plays a central role in guiding neurite growth; this implies a role for TRPC5 dysfunction in neurological disorders." (PMID 37240443, 2023).
bacterial infections (1 paper, 2018). "Further in vitro and in vivo studies addressing the potential of TRPC4/TRPC5 selective agonists as protective molecules against bacterial infections remain to be investigated." (PMID 29983857, 2018). "Despite all these evidences, the relevance of TRPC5 complexes to the SIRS associated with bacterial infections has not yet been addressed; moreover, their importance as targets for bacterial Trx has never been explored." (PMID 29983857, 2018).
gastrointestinal tumors (1 paper, 2024). "This study demonstrates that TRPC5 is significantly overexpressed in gastrointestinal tumors and is inversely associated with patient prognosis." (PMID 39309444, 2024).
neurodegenerative disease (1 paper, 2024). A disorder of the central nervous system characterized by gradual and progressive loss of neural tissue and neurologic function. "Therefore, the various pathological models demonstrated the opposite effects of TRPC1 and TRPC5 in neurodegenerative diseases and neurite outgrowth." (PMID 39000357, 2024).
psychiatric disorder (1 paper, 2018). A disorder characterized by behavioral and/or psychological abnormalities, often accompanied by physical symptoms. "Taken together, the data presented provide a strong rationale for considering TRPC4 and TRPC5 as targets for the alleviation of symptoms associated with human psychiatric disorders." (PMID 29385160, 2018).
vasculopathy (1 paper, 2009). "In this study we observed increased TRPC5, raising the possibility that the observed yolk sac vasculopathy is mediated by nitric oxide driven over-activation of TRPC5." (PMID 19156209, 2009).
TRPC5 also shares sentences with these, for which no sentence is quoted: dyslipidaemia (3 papers); amyotrophic lateral sclerosis (2); anxiety disorder (2); glioblastoma (2); Hypertension (2); metabolic disease (2); autism spectrum disorder (1); breast invasive carcinoma (1); Cataplexy (1); colitis (1); endometrial tumors (1); Glomerular sclerosis (1); hypercholesterolemia (1); hyperglycaemia (1); hypertrophy (1); Hypothermia (1); injury (1); internalizing disorder (1); kidney damage (1); meningioma (1); myocarditis (1); non-alcoholic steatohepatitis (1); ovarian carcinoma (1); panic attacks (1); papillary thyroid carcinoma (1); Parkinson disease (1); pericarditis (1); post-traumatic stress disorder (1); pulmonary arterial hypertension (1); sickle cell disease (1).
A further 3 diseases each share a sentence with TRPC5 in 1 paper.